KRAS (KRas proto-oncogene, GTPase)
Diseases named in the same sentence as KRAS in open-access papers (continued):
Sharing a sentence is not in itself a finding about the gene and the disease.
cancer (continued). "Similarly, most of the genes these variants locate on are associated with one (20.86%) or two (55.83%) indications, with exceptional BRAF, ERBB2, KRAS and EGFR associated with >10 types of cancer indications." (PMID 36856726, 2023). "Thus, it is advisable to consider the role of aberrant HBP through the dysfunction of its enzyme, resulting in abnormal O-GlcNAc in KRAS MT cancer, as supported by recent studies." (PMID 38093368, 2023). "The RAS family members HRAS, NRAS, and KRAS were the first oncogenes identified in human cancers." (PMID 36018061, 2023). "All these demonstrated a crucial role of c-Myc for KRAS-mutant cancer growth and drug resistance." (PMID 38104151, 2023). "Although the exact mechanism underlying this phenomenon is currently unknown, the use of methuosis has been suggested for treating KRAS mutant (MT) cancer." (PMID 38093368, 2023). "Similarly, median OS was significantly shorter in patients with KRAS G12C–positive cancer with mSTK11-mKEAP1 vs STK11 WT-KEAP1 WT (5.0 vs 10.9 months; aHR, 2.20; 95% CI, 1.27–3.81; p = 0.005)." (PMID 37069542, 2023). "RAS (HRAS, KRAS, and NRAS) is the most frequently mutated gene in human cancers, particularly in positions G12 and Q61, and, consequently, the inhibition of oncogenic signaling mediated by RAS has been a key challenge in the field of cancer biology." (PMID 37627277, 2023). "In addition to those targeting genes of interest, we screened 3 KRAS-amp cancer cell lines, including 2 cancer cell lines (KE-39 and YCC-1) and 1 patient-derived cell line (CAT12)." (PMID 36752207, 2023). "Furthermore, KRAS and BRAF mutations correlate with GLUT1 overexpression by cancer cells and excessive dependence on aerobic glycolysis as an energy source." (PMID 36979659, 2023). "Activation of the PI3K/AKT/mTOR pathway has been demonstrated in multiple KRAS-positive cancers." (PMID 37154160, 2023). "These mut KRAS cancers are often refractory to inhibition of the KRAS-BRAF-MEK pathway and preclinical data suggest that combinatorial pharmacological strategies involving KRAS pathway inhibitors may yield better antitumor responses." (PMID 37816716, 2023). "Together, these data indicate that SLC25A21 selectively affects KRAS-mutant cancer cells." (PMID 37937641, 2023). "However, mutant KRAS was also detected in a substantial minority of healthy samples, which limits its utility as a cancer-screening method." (PMID 36900248, 2023). "Although difficult to measure and normalize, subtle changes in TSG expression levels could influence cancer progression and metastasis, as it is now recognized for oncogenes (i.e. Myc amplification or KRAS hyperactivation)." (PMID 36998085, 2023). "Thus, ARL-17477 is an anticancer agent targeting a wide variety of cancers, but it preferentially affects CSCs and KRAS-mutant cancers." (PMID 37402770, 2023). "The targeted agents cetuximab and panitumumab, combined with chemotherapy, are an effective treatment for metastatic colon cancer, provided that certain mutations have not occurred in cancer cells (namely activating mutations in KRAS, NRAS or BRAF genes)." (PMID 37686636, 2023). "The increased rates of KRAS mutations in BRG1 mutant patients as well as the worse outcomes for patients with co-mutations may suggest a role for BRG1 in reducing the effects of oncogenic KRAS and cancer formation." (PMID 36769189, 2023). "In conclusion, our study revealed the pro-cancer role of hsa_circ_0001846 in PC, and for the first time identified the mechanism that hsa_circ_0001846 regulated KRAS by sponging miR-204-3p to promote PC progression and had the potential to become a cancer biomarker." (PMID 38081815, 2023).
cancer (continued). "Activation of Wnt/β-catenin signaling can work in conjunction with other oncogenic pathways such as KRAS in lung epithelial cells to produce a more aggressive cancer phenotype by forcing an embryonic distal progenitor phenotype and reducing E-cadherin expression." (PMID 37841927, 2023). "We report redox system regulates KRAS localization and activity via oxidation at His95 residue, and proposes a role of oncogenic K-Ras in the antioxidant-induced growth and metastasis of KRAS-driven cancers." (PMID 37666666, 2023). "To identify which of the 80 TSGs mediate the UHRF1 phenotype in KRAS mutant cancer cells, we designed a focused CRISPR library targeting those genes and used this library to perform a screen in Cas9-expressing A549 cells treated with either a non-targeting control sgRNA or an UHRF1-targeting sgRNA." (PMID 37407562, 2023). "The accurate identification of patients with KRAS or EGFR mutations is critical for the planning of individualized therapeutic strategies, as these mutations have been shown to play a significant role in cancer progression and response to treatment." (PMID 37508774, 2023). "However, it is confirmed by the computational studies that these compounds have to be studied in vitro and in vivo to evaluate their complete therapeutic potential against the KRAS G12D mutant cancers." (PMID 36975507, 2023). "Accordingly, the occurrence of KRAS mutation only is not sufficient to trigger the appearance of cancer, due to the efficacy of microRNA suppression." (PMID 37511536, 2023). "While KRAS-G12 mutations are frequent in pancreatic (91% of KRAS-mutated cases), colorectal (CRC) (68%), and lung (85%) cancers, KRAS-G13 mutations are common in gastrointestinal cancers (20% in CRC), and KRAS-Q61 alterations are common in human melanomas (85%)." (PMID 37376135, 2023). "Additionally, B-RAFV600E inhibitors surprisingly activate the MAPK pathway in KRAS mutant driven cancers." (PMID 37108538, 2023). "To determine whether ATR overexpression could impact KRAS-driven cancer development, we focused on a cohort of LUAD patients from The Cancer Genome Atlas (TCGA) and sought to determine whether the expression level of ATR impacts overall survival (OS)." (PMID 37591859, 2023). "Interestingly, pan-cancer cohort analysis indicated that KRAS-mutant patients with high ATR expression (389/907, 42.9%) had a significantly lower OS rate than patients with low ATR expression." (PMID 37591859, 2023). "KRAS mutated cancer cells, including NSCLC cells, display distinct metabolic reprogramming for cancer cell growth, proliferation, and survival and can stimulate nutrient scavenger processes such as macropinocytosis and autophagy, which generate endogenous vesicles, macropinosomes, and autophagosome." (PMID 38093368, 2023). "In the CS long–exposed mice, the correlation between let-7a expression and the number of KRAS mutations was positive (R = +0.5506) in the cancer-free mice and negative (R = −0.5568) in the cancer-bearing mice." (PMID 37511536, 2023). "About 30% of all human cancers bear activating rat sarcoma (RAS) mutations; in particular, Kirsten rat sarcoma (KRAS) mutations are considerably more frequent than Harvey rat sarcoma virus oncogene (HRAS) and Neuroblastoma RAS Viral Oncogene Homolog (NRAS) mutations." (PMID 37298264, 2023). "Additionally, it has been reported that cancer cells harboring oncogenic KRAS rely heavily on HBP for their growth and survival." (PMID 37880766, 2023). "Messenger ribonucleic acid (mRNA)-5671/V941 is a novel mRNA vaccine encoding mutant KRAS which is being studied in patients with KRASmu cancers in phase I clinical trial (NCT03948763), with or without Pembrolizumab." (PMID 37298264, 2023). "From this vantage point, the approval of adagrasib looks not so much like the beginning of the end for KRAS-mutated cancers, but something much closer to the end of the beginning." (PMID 36933199, 2023).
cancer (continued). "As mutations in RAS account for 30% of human cancer and the expression of KRasG12D in epidermal keratinocytes induces SCC formation in the skin, KRasG12D mouse models are thus widely used to discern the role of KRas in the development of cancer." (PMID 37760426, 2023). "Although ICMT inhibition might also affect other RAS proteins, such as KRAS, its constitutive activation in KRAS-mutant cancers could make it less sensitive to protein methylation disruption." (PMID 37996408, 2023). "12,33 KRAS-driven cancers are also resistant to therapies targeting RTKs such as EGFR." (PMID 36241718, 2023). "Droplet digital PCR (ddPCR) analysis of the fraction of KRAS/NRAS/BRAF mutated gene copies in kinase-rearranged tumors indicated that there was simultaneous co-occurrence of two activating events in cancer cells, but not genetic mosaicism." (PMID 37686416, 2023). "Moreover, in addition to directly binding with KRAS, several modulators that regulate KRAS signaling are also valuable in treating KRAS-mutant-driven cancer." (PMID 37110848, 2023). "We also applied the universal pegRNA to correct endogenous KRAS mutations in human cancer cells and found that G13D KRAS mutation was successfully corrected to wild-type KRAS sequences with up to 40.6% correction frequency without indel mutations." (PMID 37391511, 2023). "Other methods of targeting KRAS-mutated cancers are using pan-pathway inhibitors, most commonly targeting the downstream MAPK molecule MEK, with enhanced efficacy with combination therapy targeting the EGFR, CDK, JAK/STAT, PI3K pathways with a KRAS inhibitor." (PMID 37190303, 2023). "It is well known that activation of KRAS is regulated by EGFR signaling in cancer cells." (PMID 37649607, 2023). "Treatment resistant PDA may feature selection of KRAS wild-type cancer cells that confer a survival advantage, making them more aggressive and resistant to targeted therapy." (PMID 37404765, 2023). "Glutamine addiction extends from the context of MYC, and mutations in KRAS —a key gene related to the stability and activity of c-MYC protein— in cancer cells similarly cause dependence on exogenous glutamine for cellular growth and proliferation, as does MYC amplification." (PMID 36959802, 2023). "The discovery of transcriptomic changes involving functional effectors in KRAS-driven cancers is thus a relevant question in the field that may lead to the identification of molecular targets for novel therapeutic strategies." (PMID 37210549, 2023). "Based on these data, we propose that breaking ferroptosis resistance through the use of FSP1 inhibitors might be a particularly potent treatment strategy against KRAS-driven cancers." (PMID 36443441, 2023). "Taken together with a varying degree of dependence of cancer cells on the presence of KRASG12C mutations for growth and survival, as well as the heterogeneity of intratumoral KRAS mutation expression, our data highlight the importance of combination strategies in overcoming treatment resistance." (PMID 37907934, 2023). "In detail, KRAS mutations led to the downregulation of HLA class I on the cell surface and the overexpression of PD-L1 and CD47 with the consequent prevention of innate and adaptative anti-cancer responses." (PMID 37511856, 2023). "Amplification of KRAS, without activating missense mutations, has been described in a variety of cancers but most commonly within the CIN-type GEAs." (PMID 36752207, 2023). "KRAS mutant cancers, particularly NSCLC, respond well to dual SHP2 and MEK inhibition." (PMID 38001644, 2023).
cancer (continued). "Recent pieces of evidence report the resistance to AMG 510 among KRAS G12C-mutant cancer patients." (PMID 37396909, 2023). "This may in part explain why HRAS-transformed cells remain within epithelia on stiff substrates, and it may also help to explain why tissue fibrosis is a risk factor in the development and progression of many RAS-driven cancers, including KRAS mutant PDAC." (PMID 36175301, 2023). "To address this gap, we assessed the prognostic and predictive value of vitamin C in patients with stage IV CRC by comparing vitamin C level between cancer-free and cancer patients and analyzing the specific plasma vitamin C levels in RAS (NRAS/KRAS) and BRAF mutated CRC patients." (PMID 36969825, 2023). "Aberrant KRAS activity renders LUAD cancer cell lines vulnerable to MTHFD2 and EZH2 inhibitors." (PMID 37069494, 2023). "Alternatively, these therapies could also be used in combination with KRAS inhibitors to eliminate drug resistant or persister cancer cells." (PMID 37581538, 2023). "In particular, the fact that almost all PDACs selectively use KRAS over other RAS-GTPases may be hiding some important secret in this cancer and could be a whole new key to drug development against PDAC." (PMID 37158894, 2023). "Nevertheless, recent findings have shown that endometriotic lesions without concurrent cancers contain cancer-associated somatic mutations including for KRAS, PTEN, ARID1, and PIK3CA." (PMID 36788175, 2023). "Nevertheless, there are many GEFs (including SOS2) that can replace the function of SOS1; hence, it is unclear whether inhibiting SOS1 alone is sufficient to reduce KRAS signaling in humans to prevent cancer." (PMID 36831298, 2023). "Attempts to block factors involved in MAP kinase signaling (such as MEK and Raf) or binding partners to KRAS have shown some clinical promise in specific cancer types but have presented challenges with toxicity and eventual treatment resistance even in combination with other treatment options." (PMID 37141389, 2023). "Several of the cancer-related genes we identified, including PIK3CA, KRAS, GNAS, and PPM1D, could also have haematological mutations." (PMID 37175518, 2023). "Moreover, promoters of many oncogenes and other cancer-associated genes (e.g., MYC, KRAS) have the PQS and G4 which appear to regulate their expression." (PMID 36768357, 2023). "In addition, we have also been able to document here the unique dependence on SOS1 of human KRAS-driven LUAD by means of in silico analyses of publicly available datasets for human LUAD cancer cell lines and patients." (PMID 37730692, 2023). "Interestingly, ERK5 inhibition or MEK5 genetic deletion also sensitized NSCLC KRAS mutated A549 cells to TRAIL cytotoxicity, a model where TRAIL induces cancer progression, invasion and metastasis instead of activating apoptosis." (PMID 37919293, 2023). "Of note, drug predictions largely overlapped with those obtained using a KRAS-regulated gene signature, suggesting that JAK inhibitors may indeed function in mut KRAS cancer." (PMID 37210549, 2023). "YAP is needed for cancer progression and is a crucial player in KRAS mutant mice." (PMID 37371705, 2023). "KRAS-driven cancers are notorious for their aggressiveness and resistance to therapy." (PMID 36675307, 2023). "In view of the dependency of KRAS-driven tumors on exogenous lipids, when designing approaches to target lipid signaling it is important to consider the impact of the different extracellularly derived lipids on KRAS mutant cancer cells." (PMID 36675307, 2023). "Importantly, the mutant-specific nature of these inhibitors enables inhibition of KRAS signaling in KRAS G12C mutant cancer cells while sparing signaling in normal cells, thereby widening the therapeutic window compared with nonmutant selective inhibitors." (PMID 37581538, 2023). "It has also been suggested as a potential therapeutic target in patients with KRAS-mutant cancer." (PMID 38087254, 2023).
cancer (continued). "The findings suggest that these compounds could act as potential inhibitors of the KRAS protein, opening up new avenues for cancer management." (PMID 37822837, 2023). "Undoubtedly, mutant KRAS signaling remains the key player in anti-cancer drug development." (PMID 37110848, 2023). "Hsa-miR-17-5p is closely associated with the BP of cancer and that this regulatory role may be relevant through the PI3K/AKT and the KRAS signaling pathway." (PMID 37309005, 2023). "Drp1 supports KRas-driven cancer growth through glycolysis induction." (PMID 36831455, 2023). "Hence, only combined targeting of GPX4 and FSP1 is effective at killing KRAS-driven pancreatic organoids and FSP1 is upregulated in human KRAS-driven cancers." (PMID 36443441, 2023). "The KRAS GTPase is among the critical genetic factors driving cancer and germline conditions." (PMID 37207265, 2023). "Similar to patients with KRAS mutations, EGFR inhibitors are ineffective in BRAF mutated cancers." (PMID 37444625, 2023). "Given the critical role of RASON in promoting oncogenic KRAS signaling, we investigated whether this could be utilized for targeting KRAS-driven cancers." (PMID 36241718, 2023). "As we are studying the effect of oncogenic KRAS mutation in an adenocarcinoma cell line under CRC microenvironment mimicking culture contexts, we were particularly interested in biological processes commonly observed in cancer development." (PMID 36894174, 2023). "KRAS and EGFR mutations are common in this form of cancer and can influence treatment response." (PMID 37508774, 2023). "Regulatory proteins should be considered in KRAS-mutant NSCLC, because they might be clinically relevant to understanding the current mechanisms of resistance to KRAS G12C inhibitors and/or other forms of cancer management." (PMID 37381723, 2023). "The KRAS inhibitors ASP2453, Sotorasib and Adagrasib are the most recently developed KRAS inhibitors with comprehensive published results in vitro and in vivo on their ability to selective inhibit KRAS G12C mutated cancers and downstream pathways." (PMID 37190303, 2023). "The heterogeneity of KRAS-driven disease across cancer types can obscure patterns of dependency." (PMID 37141389, 2023). "While these studies were not conducted specifically for KRAS-mutated cancers, they do provide significant groundwork in applying immunotherapy to previously resistant cancer subsets." (PMID 37190303, 2023). "The lack of parallelism between a high level of KRAS mutation and a high intensity of let7 down regulation explains why cancer has not developed in these mice." (PMID 37511536, 2023). "Several types of cancer, including PDAC, often accumulate mutations in the KRAS oncogene." (PMID 37122717, 2023). "Recently, multiple strategies, including covalent binding strategy, targeted protein degradation strategy, targeting protein and protein interaction strategy, salt bridge strategy, and multivalent strategy, have been adopted to develop KRAS direct inhibitors for anti-cancer therapy." (PMID 37110848, 2023). "Considering that the existence of KRAS pathogenic variants results in activation of the intracellular RAS–RAF–MEK–ERK pathway, mitogen‐activated extracellular signal‐regulated kinase (MEK) inhibitors are expected to be key drugs for the treatment of KRAS‐mutant cancers." (PMID 36691316, 2023). "KRAS is one of the most frequently activated oncogenes in human cancers." (PMID 36413402, 2023). "Identifying KRAS-specific vulnerabilities helps to target KRAS-driven cancer." (PMID 37407562, 2023). "It is believed that mutated KRAS involves the epithelial-mesenchymal transition (EMT) and indicates an invasive nature that helps to facilitate the invasion and metastasis of primary cancer." (PMID 38087207, 2023). "Targeting upstream components of the ERK pathway such as the EGFR or downstream effectors such as MEK is either not recommended for the treatment of KRAS-mutated cancers or not sufficient as single agent." (PMID 37020037, 2023).